Y_RNA (Y RNA )
Gene: Miscellaneous RNA gene on chromosome 14 (99,583,017 to 99,583,118, forward strand). Ensembl gene ENSG00000200506.
Homologues: Orthologues: chimpanzee Y_RNA (99% identical), macaque Y_RNA (95% identical). Paralogues in human: RNY3 (96% identical), RNY3P1 (94% identical), Y_RNA (94% identical), Y_RNA (93% identical), Y_RNA (92% identical), Y_RNA (91% identical), Y_RNA (90% identical), Y_RNA (89% identical), RNY3P11 (88% identical), RNY3P16 (88% identical), Y_RNA (88% identical), RNY3P14 (87% identical), and 100 more.